RNU7-24P (RNA, U7 small nuclear 24 pseudogene)
Synonyms: U7.24; HSU7.25; HSU7.24; RNU7P3; U7
Gene: Small nuclear RNA gene on chromosome 16 (24,400,056 to 24,400,117, reverse strand). Ensembl gene ENSG00000239081.
Homologues: Orthologues: macaque U7 (100% identical), chimpanzee U7 (98% identical), pig U7 (85% identical). Paralogues in human: RNU7-52P (89% identical), RNU7-62P (87% identical), RNU7-7P (87% identical), RNU7-143P (85% identical), RNU7-14P (85% identical), RNU7-48P (85% identical), RNU7-1 (84% identical), RNU7-160P (84% identical), RNU7-21P (84% identical), RNU7-28P (84% identical), RNU7-2P (84% identical), RNU7-34P (84% identical), and 142 more.